LINC01055 (long independently transcribed non-coding RNA 1055)
Gene: Long non-coding RNA gene on chromosome 13 (45,680,182 to 45,701,187, reverse strand). Ensembl gene ENSG00000235366.
Diseases named in the same sentence as LINC01055 in open-access papers:
LINC01055 is named in the same sentence as 1 disease in open-access papers, as found by Europe PMC text mining. Sharing a sentence is not in itself a finding about the gene and the disease. The quoted sentences say what the papers report.
colorectal cancer (1 paper, 2022). A primary or metastatic malignant neoplasm that affects the colon or rectum. "For example, eight immune-related lncRNAs (LINC00461, LINC01055, ELFN1-AS1, LMO7-AS1, CYP4A22-AS1, AC079612.1, LINC01351, and MIR31HG) related to the prognosis of patients with colorectal cancer have been identified from TCGA database." (PMID 35144613, 2022).